GATA6 (GATA binding protein 6)
Diseases named in the same sentence as GATA6 in open-access papers (continued):
Sharing a sentence is not in itself a finding about the gene and the disease.
lymph node metastasis (7 papers, 2020 to 2025). "GATA6 down-regulation largely due to promoter hypermethylation was strongly associated with lymph-node metastasis in bladder cancer." (PMID 41514651, 2025). "High GATA6 expression correlates with better overall survival (OS) and disease-free survival (DFS), while low GATA6 expression is linked to larger tumors, a higher percentage of lymph node metastasis, and poorer differentiation." (PMID 40699746, 2025). "When compared with normal tissues, GATA6 was highly expressed in laryngeal cancer and para cancer tissues, but the expression of GATA6 in laryngeal cancer tissues was different and was highly linked with lymph node metastasis, clinical staging, and pathological grading." (PMID 34006300, 2021). "GATA6 expression was significantly associated with lymph node metastasis in 91 patients with CCA." (PMID 33060563, 2020). "Similarly, low GATA6 expression was found to be associated with lymph node metastasis and could be used as a predictive marker for reduced survival in bladder cancer." (PMID 41514651, 2025). "However, when we investigated the differences between tumor tissue and lymph node metastasis, we found that while GATA4 expression remained stable in 71% of the cases, loss of GATA6 expression was common, being detected in up to 40% of cases." (PMID 36830789, 2023). "In BCa, low expression of GATA6 could promote lymph node metastasis, which might serve as a predictor of early recurrence and short survival." (PMID 34824999, 2021). "Importantly, GATA6 expression exhibited a significant negative correlation with tumor volume, lymph node metastasis, and clinical staging of patients." (PMID 38483616, 2024).
pancreatic adenocarcinoma (7 papers, 2010 to 2025). "Numerous genes were overexpressed, some of which have previously been implicated in pancreatic adenocarcinoma (GATA6, IGFBP3, IGFBP6), while others were detected for the first time (MEMO1, RIOK3)." (PMID 20553613, 2010). "In pancreatic adenocarcinoma, GATA6 directly binds to the DKK2-promotor leading to a down-regulation of its expression and, therefore, reduces its suppressive effect on the oncogenic Wnt pathways." (PMID 33300112, 2021). "In human esophageal and pancreatic adenocarcinomas, GATA6 is amplified and may function as a prosurvival oncogene." (PMID 32157212, 2020).
atherosclerosis (6 papers, 2021 to 2025). A disease characterized by the build-up of fatty material and calcium deposition in the arterial wall resulting in partial or complete occlusion of the arterial lumen. "Injection of ApoE-/- mice with miR-10a precursor inhibited the GATA6 expression in the endothelium of atherosclerosis-susceptible region." (PMID 34336268, 2021). "In vivo results using ApoE-/- mice showed that GATA6 is overexpressed in the endothelium of atherosclerosis-susceptible region (OS region) of the cardiovascular system, but not in the endothelium of atherosclerosis-resistant region (PS region)." (PMID 34336268, 2021). "Previous studies have found that HDAC1/2 promotes arterial endothelial cell surface vascular cell adhesion molecule-1 expression and atherosclerosis through inhibition of STAT3 acetylation-dependent GATA6 promoter methylation." (PMID 38444939, 2024). "It has been noted that HDAC1 can be involved in VCAM-1 expression and promotion of atherosclerosis through inhibition of STAT3 acetylation-dependent methylation of the GATA6 promoter." (PMID 37405052, 2023). "GATA6 is an atherosclerosis-related transcription factor that protects against intimal hyperplasia." (PMID 37662558, 2023). "Despite several in vitro and in vivo reports on the anti-inflammatory effect of shear-sensitive miR-10a in ECs, the role of endothelial miR-10a/GATA6/VCAM-1 signaling during the progression of human atherosclerosis remains unclear in vivo." (PMID 34336268, 2021). "It is indicated that GATA6 may be involved in the process of atherosclerosis in patients with CAE." (PMID 37662558, 2023). "This study aimed to identify the expression patterns of miR-10a/GATA6/VCAM-1 in vivo and study their implications in the pathophysiology of human coronary artery disease (CAD), i.e., atherosclerosis." (PMID 34336268, 2021). "Our findings suggest that low miR-10a and high GATA6/VCAM-1 in the cardiovascular endothelium correlates to the development of human atherosclerotic lesions, suggesting that miR-10a signaling has the potential to be developed as a biomarker for human atherosclerosis." (PMID 34336268, 2021). "Moreover, GATA6/VCAM-1 (a downstream target of miR-10a) was highly expressed in the endothelium, accompanied by the reduced levels of miR-10a during the development of human atherosclerosis." (PMID 34336268, 2021).
COVID-19 (6 papers, 2022 to 2025). A disease caused by infection with severe acute respiratory syndrome coronavirus 2. "Among them, six genes (CXCR4, ENO1, FASN, GATA6, PDK1 and TUBB3) have been reported to be associated with the pathological mechanism of COVID-19 and OA." (PMID 37291167, 2023). "Elevated expression of GATA6 has been observed in COVID-19 patients compared with healthy individuals indicating the clinical relevance of GATA6 to SARS-CoV-2 infection." (PMID 37520399, 2023). "Analysis of clinical samples collected from SARS-CoV-2 infected individuals shows elevated levels of GATA6, suggesting a role in COVID-19 pathogenesis." (PMID 35469023, 2022). "ENO1 and TUBB3 were found to be probably related to the progression of OA, while FASN and GATA6 may participate in COVID-19." (PMID 37291167, 2023). "It was found that both GATA6 and SFTPA genes were overexpressed in lung tissues from COVID-19 patients, while LMCD1 (the GATA6 antagonist) was underexpressed." (PMID 36551272, 2022). "Further, sustained decrease in testosterone levels along with the downregulated steroidogenesis genes (GATA6 and GATA1) indicate a long-term impact on LC function and aligns well with clinical data showing decreased testosterone levels in COVID-19 patients for up to 7 months after recovery." (PMID 39775442, 2025).
prostate carcinoma (6 papers, 2017 to 2023). A carcinoma that arises from epithelial cells of the prostate gland. "In this study, we find that LINC00261-targeted GATA6 suppresses the proliferation, migration, invasion and angiogenesis of prostate cancer by promoting activation of DKK3." (PMID 33013201, 2020). "Here we explore the functional relationships between LINC00261, DKK3, and GATA6 as well as their roles in prostate cancer in order to uncover a promising strategy for prostate cancer treatment." (PMID 33013201, 2020). "LINC00261, GATA6 as well as DKK3 expression in prostate cancer was down-regulated." (PMID 33013201, 2020). "Furthermore, the LINC00261/GATA6/DKK3 axis plays a crucial role in the development and prostate cancer progression; LINC00261-targeted GATA6 suppressed the proliferation, migration, invasion and angiogenesis of prostate cancer by promoting activation of DKK3." (PMID 33013201, 2020). "An earlier study showed KRT80, RUNX, GATA6, SERPINB13, and SLC6a14 are important markers for prostate cancer progression, whereas we also identified KRT80, RUNX as well as GATA2, GATA2-AS1 in our study." (PMID 37476073, 2023). "Niraparib restrains prostate cancer cell proliferation and metastasis and tumor growth in mice by regulating the lncRNA MEG3/miR-181-5p/GATA6 pathway." (PMID 38047026, 2023). "Therefore, it is reasonable to predict GATA6 could be related to prostate cancer development." (PMID 33013201, 2020). "Furthermore, validation with GEPIA database revealed that DKK3 expression was also decreased in prostate cancer, which further demonstrated that LINC00261 might regulate DKK3 by binding to transcription factor GATA6, thus affecting the development of prostate cancer." (PMID 33013201, 2020). "In prostate cancer, the overexpression of LINC00261 was shown to inhibit the transcription of dickkopf-related protein 3 (DKK3) by recruiting GATA binding protein 6 (GATA6), resulting in the inhibition of tumor angiogenesis; this action was reversed by silencing DKK3." (PMID 34022894, 2021). "LINC00261, GATA6, and DKK3 were poorly expressed in prostate cancer." (PMID 33013201, 2020). "Moreover, 8 of these TFs (FOXJ2, GATA6, NFE2L1, NFIL3, PRRX2, TEF, EBF2 and ZBTB18) were found to be differentially expressed in this study making them not only candidate biomarkers of prostate cancer but also potential therapeutic targets." (PMID 28380430, 2017).
Tetralogy of Fallot (6 papers, 2017 to 2026). A congenital cardiac malformation comprising pulmonary stenosis, overriding aorta, ventricular septum defect, and right ventricular hypertrophy. "Cardiac: GATA6 haploinsufficiency is strongly associated with congenital heart defects (e.g., Tetralogy of Fallot)." (PMID 41614934, 2026). "Mutations in NKX2-5 (5q35.1), GATA4 (8q23.1), ZFPM2 (8q23.1), GATA6 (18q11.2), GDF1 (19p13.11), JAG1 (20p12.2), and TBX1 (22q11.21) have been reported in sporadic cases with tetralogy of Fallot; however, interaction of these genes and FMR1 gene has never been reported." (PMID 28751920, 2017).
acne (5 papers, 2020 to 2025). An inflammatory process of the sebaceous glands which is characterized by comedones, nodules, papules and/or pustules on the skin. "In contrast, hypoxia-induced microRNA-181b has been shown to target GATA6, thus eventually destabilizing GATA6-controlled infundibular keratinocyte homeostasis, linking ductal hypoxia to ductal GATA6 deficiency in acne." (PMID 37998335, 2023). "Expression levels of GATA6 are reduced in early acne lesions, resulting in increased acne-driven cytokines." (PMID 38357543, 2024). "GATA6 expressed in differentiating sebocytes can induce the expression of IL-10 and negatively regulates acne-driven IL-8 and IL-17 cytokines." (PMID 38357543, 2024). "GATA6 expression contributes to the therapeutic effect of retinoic acid, the main treatment for acne." (PMID 33082341, 2020). "In both datasets, GATA6 expression was decreased in acne skin, although the difference was only significant in the larger dataset." (PMID 33082341, 2020). "At puberty onset, upregulation of AR signalling is likely to explain the downregulation of GATA6 we observe in acne samples." (PMID 33082341, 2020). "Here we show that GATA6, which is expressed in the upper pilosebaceous unit of normal human skin, is down-regulated in acne." (PMID 33082341, 2020). "We next examined GATA6 expression in skin biopsies from five healthy controls and nine acne patients presenting with different degrees of disease severity." (PMID 33082341, 2020). "The reduction in GATA6 expression in acne was further supported by reanalysing published microarray datasets comparing acne skin with matched healthy skin from the same patients or from control patients." (PMID 33082341, 2020). "GATA6 expression was reduced in comedone walls of early acne lesions and was completely lost in advanced lesions." (PMID 33082341, 2020). "GATA6 controls the proliferation and differentiation of keratinocytes to prevent the hyperkeratinization of the infundibulum, which is the primary pathological event in acne vulgaris (comedogenesis)." (PMID 37998335, 2023). "Therefore, one would predict that GATA6 downstream targets would be silenced in acne since GATA6 is reduced." (PMID 33082341, 2020). "In this work, we show that GATA6 expression is reduced in human acne skin." (PMID 33082341, 2020). "We conclude that GATA6 is involved in regulation of the upper pilosebaceous unit and may be an actionable target in the treatment of acne." (PMID 33082341, 2020). "GATA6 controls keratinocyte proliferation and differentiation to prevent hyperkeratinisation of the infundibulum, which is the primary pathological event in acne." (PMID 33082341, 2020). "The observed downregulation of GATA6 in acne samples led us to hypothesise that GATA6 could be involved in the physiological maintenance of the upper pilosebaceous unit in humans." (PMID 33082341, 2020). "Here the authors show that GATA6 is involved in maintaining homeostasis of the upper pilosebaceous unit of human skin and may contribute to acne pathogenesis." (PMID 33082341, 2020). "Our work provides evidence that GATA6 controls several physiological processes contributing to homoeostasis of the upper pilosebaceous unit in human skin, and that its expression is markedly reduced in acne skin." (PMID 33082341, 2020). "Overall, our findings demonstrate that GATA6 is involved in human upper HF homoeostasis and may contribute to acne pathogenesis." (PMID 33082341, 2020). "In the vicinity of acne lesions in which GATA6 was lost, we observed thicker and more proliferative IFE, reinforcing the hypothesis that GATA6 negatively controls IFE fate." (PMID 33082341, 2020).
acne (continued). "Some target genes were likely involved in acne development, including AR, IGF1/IGF1R, mTOR, GATA6, Wnt, IL6, FOXO1, PIK3, MYC." (PMID 40625748, 2025). "We conclude that GATA6 expression is decreased or lost in acne lesions, regardless of their severity." (PMID 33082341, 2020). "This suggested that the decrease in GATA6 was not a consequence of the increased inflammation in severe acne lesions." (PMID 33082341, 2020). "The topical treatment of acne with all-trans retinoic acid (ATRA) and its systemic treatment with isotretinoin, the precursor of ATRA, may thus normalize disturbed follicular keratinization, promoting comedolysis via the induction of GATA6 expression." (PMID 37998335, 2023). "We postulated that GATA6 could be involved in the differentiation of cells of the INF/JZ/SD on the one hand and of SG on the other hand, as in the comedone switch hypothesis, and could therefore be involved in acne pathogenesis." (PMID 33082341, 2020).
adenoma (5 papers, 2008 to 2024). A neoplasm arising from the epithelium. "GATA6, identified as an important gene in our random forest model, exhibited a higher mutation rate in adenomas than in CRC." (PMID 39554798, 2024). "Across K and KP models, GATA6 was predominantly expressed in epithelial hyperplasia, with its levels increasing as adenomas progress (Grades 1–3) and heterogeneously decreasing in late stage adenocarcinomas (Grade 4)." (PMID 32157212, 2020).
astrocytoma (5 papers, 2008 to 2020). "In particular, loss-of-function GATA6 in human astrocytes may lead to the acceleration of tumorigenesis, suggesting its tumor suppressor role in astrocytoma." (PMID 27689399, 2016). "Indeed, GATA6 has been characterized as a TSG in other cell contexts, and inactivating mutations have been identified in human malignant astrocytomas." (PMID 18535672, 2008).
glioblastoma (5 papers, 2012 to 2021). The most malignant astrocytic tumor (WHO grade IV). "Loss of expression of GATA4 and GATA6 occurs in glioblastoma multiforme (GBM)." (PMID 26953528, 2016). "GATA6 is suppressed via CpG island hypermethylation in glioblastoma, suggesting it normally limits proliferation." (PMID 29415247, 2018). "Newly obtained influence of GATA6 hypermethylation on glioblastoma patient survival in a small group of tumors was shown as a promising marker in prognostic purposes." (PMID 22672670, 2012). "Gata6’s role in mammalian neurogenesis was unknown but hypermethylation represses Gata6 in glioblastomas, suggesting Gata6 normally limits proliferation." (PMID 29415247, 2018). "The current study reveals new and important information on MGMT, GATA6 and CASP8 promoter methylation in glioblastoma." (PMID 22672670, 2012). "High methylation frequency of tested genes shows heterogeneity of glioblastoma epigenome and the importance of MGMT, GATA6 and CASP8 genes methylation in glioblastoma patient outcome." (PMID 22672670, 2012). "Cox regression analysis showed patient age, treatment, MGMT, GATA6 and CASP8 as independent predictors for glioblastoma patient outcome (p < 0.05)." (PMID 22672670, 2012). "In glioblastoma specimens gene methylation was observed as follows: MGMT in 51.3%, GATA6 in 68.4%, CD81 in 46.1%, DR4 in 41.3% and CASP8 in 56.8% of tumors." (PMID 22672670, 2012). "The methylation status of MGMT, CD81, GATA6, DR4, and CASP8 in 76 patients with primary glioblastomas was investigated." (PMID 22672670, 2012). "It has been suggested that in glioblastoma, highly methylated genes, such as CD81 (CD81 antigen), DR4 (death receptor 4, TRAIL receptor 1) and GATA6 (GATA binding protein 6), participating in cell adhesion, apoptosis, and proliferation could be important in gliomagenesis." (PMID 22672670, 2012).
heart failure (5 papers, 2013 to 2025). Inability of the heart to pump blood at an adequate rate to meet tissue metabolic requirements. "Cardiomyocyte specific deletion of GATA-4 or GATA-6 in adult mice leads to heart failure during pathological pressure overload." (PMID 33876316, 2021). "By comparison, cardiac-specific deletion of Gata6 similarly resulted in a defective hypertrophic response with pressure overload stimulation, as well as a greater propensity towards heart failure." (PMID 24391969, 2013). "While single deletion of Gata4 or Gata6 in activated cardiac fibroblasts did not exert any phenotypic effect on cardiac function, we found a more decreased systolic function and signs of aggravated heart failure in mice with combined deletion of Gata4 and Gata6 in heart fibroblasts." (PMID 33876316, 2021). "Our case is unique because it is the first case of this novel GATA6 variant in a family with a paternal history of CHD and an infant with severe CHD that affects the right-side structures and the ventricular septum leading to early heart failure requiring heart transplant." (PMID 40076735, 2025). "Indeed, we have previously shown that hearts from Gata4 cardiac-specific targeted mice had a defect in cardiac angiogenesis following stress stimulation that then directly predisposed to heart failure, although the role of Gata6 in this process was not analyzed." (PMID 24391969, 2013). "In contrast, we found that overexpressed Myc bound both the promoter region and body of many cardiac-specific genes including transcription factors (Gata4, Gata6, Tbx20, Nkx2-5), structural genes (Actc1, Pln), or heart failure related genes (Nppa, Nppb), but did not induce Pol II recruitment." (PMID 27346836, 2016). "However, non-redundant functions were identified in allowing the heart to compensate and resist heart failure after pressure overload stimulation, as neither Gata4 nor Gata6 deletion was fully rescued by expression of the reciprocal transgene." (PMID 24391969, 2013).
non-small cell lung carcinoma (5 papers, 2020 to 2025). A group of at least three distinct histological types of lung cancer, including non-small cell squamous cell carcinoma, adenocarcinoma, and large cell carcinoma. "Upregulation of GATA6, a transcription factor that mediates the expression of autophagy-related genes such as ATG5, ATG7, and ATG12 by erlotinib treatment promotes treatment resistance in cellular models of non-small cell lung cancer (NSCLC)." (PMID 32245178, 2020). "However, a recent study has shown that CD14hi/Tim4+ PRMs in peritoneal ascites from patients with peritoneal metastatic non-small cell lung cancer do not express GATA6." (PMID 35401237, 2022).